CMAS (cytidine monophosphate N-acetylneuraminic acid synthetase)
Description:
Catalyzes the activation of N-acetylneuraminic acid (NeuNAc) to cytidine 5'-monophosphate N-acetylneuraminic acid (CMP-NeuNAc), a substrate required for the addition of sialic acid. Has some activity toward NeuNAc, N-glycolylneuraminic acid (Neu5Gc) or 2-keto-3-deoxy-D-glycero-D-galacto-nononic acid (KDN).
Synonyms: CSS
Tractability: PROTAC: ubiquitination databases record sites on it; its protein half-life has been measured.
Gene: Protein-coding gene on chromosome 12 (22,046,174 to 22,065,674, forward strand). Ensembl gene ENSG00000111726.
Subcellular location: Nucleus
Subcellular location (Human Protein Atlas): Cytosol; Nucleoli
Pathways (Reactome):
Metabolism of proteins: Sialic acid metabolism
Gene Ontology:
Molecular function: N-acylneuraminate cytidylyltransferase activity
Biological process: CMP-N-acetylneuraminate biosynthetic process; N-acetylneuraminate metabolic process
Cellular component: membrane; nucleolus; nucleus; nucleoplasm
Genetic constraint (gnomAD): Loss-of-function variants: 13 observed, 36.52 expected, observed/expected ratio (o/e) 0.36, 90% interval 0.23 to 0.57. The upper end of that interval is the gene's LOEUF score, 0.57, which puts it in group 2 of 6, group 1 being the genes least tolerant of losing a copy. Missense variants: 312 observed, 417.83 expected, observed/expected ratio (o/e) 0.75, 90% interval 0.68 to 0.82. Synonymous variants: 157 observed, 158.74 expected, observed/expected ratio (o/e) 0.99, 90% interval 0.87 to 1.13.
Homologues: Orthologues: chimpanzee CMAS (99% identical), macaque CMAS (99% identical), dog CMAS (98% identical), guinea pig CMAS (97% identical), rabbit CMAS (95% identical), pig CMAS (95% identical), mouse Cmas (94% identical), rat Cmas (94% identical), tropical clawed frog cmas (57% identical), zebrafish cmasa (55% identical), Drosophila melanogaster Csas (19% identical).
Diseases named in the same sentence as CMAS in open-access papers:
CMAS is named in the same sentence as 21 diseases in open-access papers, as found by Europe PMC text mining. Sharing a sentence is not in itself a finding about the gene and the disease. The quoted sentences say what the papers report.
breast carcinoma (4 papers, 2018 to 2025). "CMAS, which is in the sialic acid pathway, has a key role in breast cancer and is significantly associated with decreased breast cancer patient survival." (PMID 32341755, 2020). "CMAS is a protein-coding gene and participates in protein metabolism, it was reported to significantly associated with metastasis which decreases breast cancer survival." (PMID 31448219, 2019). "We additionally find that genes in the sialic acid pathway, GNE and CMAS, are significantly associated with decreased breast cancer patient survival." (PMID 29892572, 2018). "The activity of CMAS, responsible for converting Neu5Ac to CMP-Neu5Ac, has been described to be significantly associated with decreased survival of breast cancer." (PMID 40718829, 2025).
lung adenocarcinoma (2 papers, 2019 to 2025). A carcinoma that arises from the lung and is characterized by the presence of malignant glandular epithelial cells. "We found that CMAS and SLC35A1 correlated with worse survival outcomes in lung adenocarcinoma." (PMID 40718829, 2025).
autosomal recessive intellectual disability (1 paper, 2025). "The importance of the dimerization region for the biological function of human CMAS was underscored by the finding that a missense mutation in this region (R188H) causes autosomal recessive intellectual disability." (PMID 40204091, 2025).
colorectal cancer (1 paper, 2024). A primary or metastatic malignant neoplasm that affects the colon or rectum. "We previously reported that the knockout of CMAS, a key enzyme in this pathway, leads to a more aggressive tumor in a mouse model of colorectal cancer." (PMID 38384845, 2024).
pancreatic ductal carcinoma (1 paper, 2025). "Previously, we found that CMAS KO in a murine model resulted in enhanced infiltration of CD4+ and CD8+ T cells within the tumor microenvironment of pancreatic ductal carcinoma and improved survival outcomes." (PMID 40718829, 2025).
viral infections (1 paper, 2025). "It is evident that CMAS and NANS are more dynamically regulated than GNE, particularly in mono-viral infections where both genes as upregulated, as shown in heatmap." (PMID 41278481, 2025).
tumor (8 papers, 2018 to 2025). "CMP-sialic acid synthase (CMAS) knockdown in PDAC revealed that sialic acids in tumor cells induce an immunosuppressive environment by increasing IL-10 secretion and CD206 expression." (PMID 39727942, 2024). "The authors also noted that CMAS knockdown of MDA-MB-231–derived cells impaired serum-free survival and tumor xenograft growth in immune-deficient mice." (PMID 29892572, 2018). "Importantly, the co-culture with the CMAS KO tumour cells showed reduced IL-10 production." (PMID 33627655, 2021). "Tumor cells highly expressed donor synthesis genes (NANS, CMAS, and the transporter SLC35A1), while the stroma showed enriched expression of sialyltransferases involved in α2-3, α2-6 and α2-8 sialylation (ST3GAL2, ST3GAL5, ST6GAL2, ST6GALNAC5, ST6GALNAC6, ST8SIA1 and ST8SIA2)." (PMID 38594506, 2024).
cancer (6 papers, 2016 to 2024). A tumor composed of atypical neoplastic, often pleomorphic cells that invade other tissues. "We have conducted an integrated analysis of genomic, epigenomic, and transcriptomic data to estimate how the key SA genes, namely CMAS, ST3GAL1, ST3GAL5, and NEU1, are regulated across different cancer types." (PMID 32296639, 2020). "We found that mRNAs as ceRNA counterparts of lncRNA biomarkers were involved in three GO biological processes (cell death, cell adhesion and cell cycle) and four KEGG pathways (pathways in cancer, ECM-receptor interaction, cell adhesion molecules (CMAs) and adherens junction)." (PMID 27487139, 2016).
infection (5 papers, 2020 to 2025). The state of being infected such as from the introduction of a foreign agent such as serum, vaccine, antigenic substance or organism. "As expected from our previous results, CMAS KO cells were less susceptible to infection with EV-D70 and EV-D111 than control cells." (PMID 40358210, 2025). "A fraction of CMAS KO cells may thus still be susceptible to infection, which would explain why there is a small percentage of infected cells at 8 hpi." (PMID 40358210, 2025). "Approximately 15% of NT KO cells were infected at 8 hpi, while only 1% of the CMAS KO was infected, confirming that CMAS KO cells were refractory to EV-D111 infection." (PMID 40358210, 2025). "Despite this limitation of the cellular model, our results showed that CMAS KO cells are resistant to EV-D111 infection." (PMID 40358210, 2025). "CMAS KO reduced infection of several IAV strains, including PR/8 (H1N1), pdm2009 (H1N1), and IAV strain HK/68 (H3N2) to similar degrees." (PMID 39887213, 2025). "CMAS KO A549 cells were treated with several doses of sialidase prior to infection." (PMID 39887213, 2025). "IAV WSN/33 infection was significantly reduced in CMAS KO compared with parent cells." (PMID 39887213, 2025). "Knockout of CMAS, a key enzyme in sialic acid biosynthesis, significantly reduced IAV binding and infection by disrupting sialic acid production on the cell surface." (PMID 39887213, 2025). "Consequently, we demonstrate that CMAS KO cells are less permissive to IAV infection due to impaired virus binding and that sialidase treatment eliminates any residual infection." (PMID 39887213, 2025).
CMAS also shares sentences with these, for which no sentence is quoted: avian influenza (1 paper); bacterial infections (1); bacterial meningitis (1); Duchenne muscular dystrophy (1); epilepsy (1); hematoma (1); Hypertension (1); infectious disease (1); influenza (1); Macrocephaly (1); metabolic disease (1); otitis media (1).